ALDH1L2 (aldehyde dehydrogenase 1 family member L2)
Diseases named in the same sentence as ALDH1L2 in open-access papers:
ALDH1L2 is named in the same sentence as 32 diseases in open-access papers, as found by Europe PMC text mining. Sharing a sentence is not in itself a finding about the gene and the disease. The quoted sentences say what the papers report.
breast cancer (6 papers, 2015 to 2025). A primary or metastatic malignant neoplasm involving the breast. "In breast cancer, ALDH1L2 suppresses reactive oxygen species production and is involved in the MAPK pathway." (PMID 40005897, 2025). "As a result, while deletion of ALDH1L2 in breast cancer cell lines led to more ROS, it also increased mitochondrial protein synthesis." (PMID 38698089, 2024). "Supporting this idea, overexpression of ALDH1L2 in cancer cells, decreasing the production of fMet, led to reduced numbers of neutrophils in a murine breast cancer models." (PMID 38698089, 2024). "Similarly, ALDH1L2 depletion has been shown to increase mitochondrial ROS levels in breast cancer cells." (PMID 38698089, 2024). "Contrarily, a recent study found that enhancement of ALDH1L2 expression could inhibit the metastatic capability of breast cancer cells." (PMID 39513106, 2024). "ALDH1L2 has been previously proven to have correlation with EMP2 in breast cancer cells." (PMID 35799115, 2022). "The top target differentiating the Aldh1l2 KO group from the WT/Aldh1l1 KO group is interferon gamma, which would be in agreement with recent findings that interferon signaling is responsive to folate status in murine mammary cancer cells." (PMID 33168096, 2020).
melanoma (6 papers, 2017 to 2024). A malignant, usually aggressive tumor composed of atypical, neoplastic melanocytes. "In melanoma, inhibition of folate metabolism with methotrexate or ALDH1L2 knockdown decreases NADPH production and increases ROS100." (PMID 38698089, 2024). "It has been reported that ALDH1L2 exhibits abnormal expression levels in several human cancers, including CRC, melanomas, ovarian cancer and pancreatic cancer." (PMID 35597868, 2022). "Two NADPH-generating enzymes, ALDH1L2 and MTHFD1, were identified as suppressors of ROS-mediated toxicity in metastasizing melanoma cells." (PMID 28181495, 2017). "Previous study suggested that ALDH1L2 knockdown could inhibit distant metastasis without significantly affecting the growth of subcutaneous tumors in the melanoma mice models." (PMID 34150627, 2021).
colorectal cancer (4 papers, 2022 to 2024). A primary or metastatic malignant neoplasm that affects the colon or rectum. "In this study, we observed the significant overexpression of ALDH1L2 in colorectal cancer (CRC) tissues, which is associated with poor prognosis." (PMID 37507016, 2023). "Indeed, expression of 1CM-related genes as ALDH1L2 has been associated with the response to chemotherapy with 5-FU (5-fluorouracil, inhibitor of folate metabolism) in colorectal cancer patients." (PMID 39125744, 2024). "Interestingly, the chemotherapeutic agent 5-fluorouracil (5-Fu) inhibits the expression of SIRT3 and increases the acetylation levels of ALDH1L2 in colorectal cancer cells." (PMID 37507016, 2023). "To determine whether ALDH1L2 inhibits radioresistance in vivo, we employed a xenograft colorectal cancer model." (PMID 35597868, 2022).
colorectal tumor (2 papers, 2020 to 2025). "Expression of the mitochondrial folate metabolism enzymes SHMT2, MTHFD2, and ALDH1L2 was upregulated in colorectal tumor tissues, and their high expression correlated with poor patient prognosis." (PMID 41154660, 2025). "In contrast to the cytosolic enzyme, ALDH1L2 is expressed in cancer cell lines and is upregulated in colorectal tumor tissues." (PMID 33168096, 2020).
glioblastoma (2 papers, 2022 to 2025). The most malignant astrocytic tumor (WHO grade IV). "This highlights the importance of ALDH1L2 in maintaining redox balance and protecting glioblastoma stem cells from oxidative stress." (PMID 41009025, 2025). "As this earlier work indicated that ALDH1L2, a folate-dependent mitochondria aldehyde dehydrogenase gene, is upregulated in glioblastoma stem cells, we invalidated this gene using CRISPR-cas 9 technique in this present work." (PMID 35565854, 2022). "To test, we produced two lines of ALDH1L2 KO U251 glioblastoma cells using the CRISPR-Cas 9 targeting exon 1 and exon 3 of the human ALDH1L2, respectively." (PMID 35565854, 2022). "This earlier work revealed that mitochondria folate enzyme ALDH1L2 is much more expressed in TS than in differentiated glioblastoma cells; in addition, the growth of the TS cells is much more methionine dependent than that of the differentiated cells." (PMID 35565854, 2022). "In the present study, we hypothesized that ALDH1L2 is crucial for the formation of tumor spheres in glioblastoma." (PMID 35565854, 2022). "The impact of reduced NADPH levels on overall ROS levels of the ALDH1L2 KO TS cells were examined as ROS has been established as a negative regulator for stemness genes in both normal as well as cancer stem cells including glioblastoma stem-like cells." (PMID 35565854, 2022).
liver cancer (2 papers, 2021 to 2022). An epithelial or non-epithelial malignant neoplasm that arises from the liver. "The results showed that ALDH1A1, ALDH1L1, ALDH1L2, ALDH3A1, ALDH3A2, ALDH5A1, and ALDH8A1 gene expressions were significantly different between liver cancer and normal tissues." (PMID 34928471, 2022).
lung carcinoma (2 papers, 2021 to 2025). "All in-frame fusions involved genes with unknown oncogenic function by OncoKB, except for a single fusion involving ALDH1L2—a folate regulatory enzyme considered likely oncogenic, but with no established role in lung cancer or neuroendocrine cancers." (PMID 39185963, 2025).
Obesity (2 papers, 2020 to 2023). Accumulation of substantial excess body fat. "For example, elevated plasma levels of C3 and C5 acylcarnitines, the phenomenon linked to the ALDH1L2 loss, could be associated with obesity, metabolic syndrome, insulin resistance, and type 2 diabetes." (PMID 33168096, 2020). "The potential relevance of AIF1-dependent catecholamine catabolism to human obesity is supported by the positive correlation of AIF1 with MAOA and ALDH1L2 transcript levels in adipose tissues from participants with weight excess or obesity." (PMID 36596796, 2023). "In addition, we provide evidence linking these findings to human obesity, in that AIF1 expression correlates positively with MAOA and ALDH1L2 levels in adipose tissues from individuals with weight excess or obesity." (PMID 36596796, 2023).
ovarian carcinoma (2 papers, 2022 to 2023). A malignant neoplasm originating from the surface ovarian epithelium. "In addition, decreased ALDH1L2 expression has been reported in ALDH1L2 oxaliplatin-resistant CRC and ovarian cancer cell lines." (PMID 35597868, 2022).
pancreatic cancer (2 papers, 2022 to 2026). "A previous study also found that ALDH1L2 is abnormally expressed in human colorectal and pancreatic cancer tissues and that this is associated with poor recurrence-free and overall survival in patients." (PMID 35597868, 2022). "ALDH1L2 loss elevates ROS and promotes ADM in a model of pancreatitis and accelerates tumour progression in models of pancreatic cancer." (PMID 41922744, 2026).
COVID-19 (1 paper, 2024). A disease caused by infection with severe acute respiratory syndrome coronavirus 2. "Specifically, ALDH1L2 (AUC: 1) showed the best diagnostic efficiency for differentiation in the COVID-19 dataset, whereas KLF5 (AUC: 0.803) demonstrated the best discriminatory ability in the sarcopenia dataset." (PMID 38978778, 2024). "The ROC curves for ALDH1L2 and KLF5 genes demonstrated their potential as diagnostic markers for both sarcopenia and COVID-19." (PMID 38978778, 2024).
diabetes (1 paper, 2020). "Though future studies should shed light on the role of ALDH1L2 in diabetes, changes of several metabolites in Aldh1l2 KO mice recorded in the present work indicate the link between Aldh1l2 and diabetes." (PMID 33168096, 2020). "The role of ALDH1L2 in the regulation of mitochondrial function, β-oxidation, and acylcarnitine levels suggests that the enzyme could be especially relevant to diabetes." (PMID 33168096, 2020).
glioma (1 paper, 2021). A benign or malignant brain and spinal cord tumor that arises from glial cells (astrocytes, oligodendrocytes, ependymal cells). "Analysis of the TCGA dataset showed that ALDH16A1, ALDH3B1, ALDH1A3, ALDH3A1, ALDH7A1 were significantly increased in IDH wildtype gliomas, while ALDH2, ALDH6A1, ALDH5A1, ALDH1A1, ALDH1L2, ALDH18A1, ALDH1B1 expression were higher in IDH mutant gliomas than IDH wildtype gliomas." (PMID 35116021, 2021).
hepatoblastoma (1 paper, 2024). Hepatoblastoma (HB) is a malignant hepatic tumor and is the most common pediatric liver cancer. "One-carbon metabolism deregulation in hepatoblastoma tumors implicated 5-methyltetrahydrofolate-homocysteine methyltransferase (MTR), aldehyde dehydrogenase 1 family member L2 (ALDH1L2), and methylenetetrahydrofolate dehydrogenase (NADP+-dependent) 1-like (MTHFD1L)." (PMID 39684755, 2024).
rectal cancer (1 paper, 2022). A primary or metastatic malignant neoplasm that affects the rectum. "We then assessed the expression of ALDH1L2 mRNA in the GEO datasets, GSE46862, GSE93375 and GSE133057, observing that ALDH1L2 mRNA levels were significantly lower in patients with rectal cancer who were non-responsive to neoadjuvant radiochemotherapy than in responsive patients." (PMID 35597868, 2022).
renal fibrosis (1 paper, 2023). A final common manifestation of a wide variety of chronic kidney diseases characterized by glomerulosclerosis and tubulointerstitial fibrosis. "Renal fibrosis in UUO was associated with a remarkable loss of ALDH1L2 in a large portion of renal tubules, which was prevented by anti-mir-219a-5p." (PMID 37333081, 2023). "These analyses identified ALDH1L2 as a direct target of mir-219a-5p in renal fibrosis, especially fibronectin expression." (PMID 37333081, 2023). "Altogether, these results demonstrate the important role of ALDH1L2 as a mir-219a-5p target in renal fibrosis." (PMID 37333081, 2023). "In our experiment, the knockdown of ALDH1L2 significantly enhanced fibronectin expression during TGF-β1 treatment, suggesting that ALDH1L2 is a key downstream target of mir-219a-5p to regulate renal fibrosis." (PMID 37333081, 2023). "Although we confirmed ALDH1L2 as a direct target of mir-219a-5p in renal fibrosis, other target genes of mir-219a-5p may modulate ECM remodeling and collagen deposition as well." (PMID 37333081, 2023). "ALDH1L2 was identified to be the direct target gene of mir-219a-5p in renal fibrosis." (PMID 37333081, 2023). "Together, these data indicate that ALDH1L2 is a direct target of mir-219a-5p in renal fibrosis." (PMID 37333081, 2023). "Upon expression, ALDH1L2 promotes GSH to suppress PAI-1 expression, resulting in fibronectin degradation and less renal fibrosis." (PMID 37333081, 2023).
cancer (18 papers, 2017 to 2026). A tumor composed of atypical neoplastic, often pleomorphic cells that invade other tissues. "At present, only few reports have investigated the role of ALDH1L2 in cancer progression and a recent study revealed that its abnormal expression was associated with radio-resistance in CRC." (PMID 37507016, 2023). "The folate cycle depends on a series of key cellular enzymes, including aldehyde dehydrogenase 1 family member L2 (ALDH1L2) that is usually overexpressed in cancer cells, but the regulatory mechanism of ALDH1L2 remains undefined." (PMID 37507016, 2023). "Many one carbon metabolic enzymes, including SHMT2, MTHFD2, and ALDH1L2, are highly expressed in human cancers, but how their activities are regulated is poorly understood." (PMID 37507016, 2023). "In contrast to its cytosolic homolog ALDH1L1, ALDH1L2 is usually overexpressed in cancer cells, suggesting its potential role in tumorigenesis and progression." (PMID 37507016, 2023). "The knockout of ALDH1L2 gene in U251 cells rendered the growth of the cancer stem cells of U251 methionine independent." (PMID 35565854, 2022). "We also suggest that the increase in NADPH production generated by the upregulation of ALDH1L2 is used to reduce the ROS level, a condition needed to maintain the stemness characteristic of the cancer stem cells." (PMID 35565854, 2022). "Several isoforms of the ALDH1 family (ALDH1A1, ALDH1A2, ALDH1A3, ALDH1B1, ALDH1L1, and ALDH1L2) are used as cancer stem cell markers in a variety of cancers." (PMID 34680942, 2021). "Silencing of ALDH1L2 in tumour cells leads to increased production of both formate and fMet, accompanied by enhanced signalling through the formyl-peptide receptor expressed by cancer cells." (PMID 38698089, 2024). "In summary, our study not only provides a potential strategy for cancer therapy by targeting the K70 site of ALDH1L2 but also suggests that the combination of SIRT3 inhibitor and 5-Fu may overcome 5-Fu resistance." (PMID 37507016, 2023). "Furthermore, the K70Q mutant of ALDH1L2 sensitizes cancer cells to 5-Fu both in vitro and in vivo through perturbing cellular redox and serine metabolism." (PMID 37507016, 2023). "It was reported that in cultured cancer cells ALDH1L2 is a primary contributor to mitochondrial NADPH and thus may be involved in the oxidative stress response mechanism." (PMID 33168096, 2020). "In particular, ALDH1L2 overexpression in cancer cells importantly contributes to NADPH generation." (PMID 28649560, 2017). "Interestingly, ALDH1L2 is overexpressed in several cancer cell lines, highlighting the importance of mitochondrial NADPH pool maintenance in cancer cells." (PMID 28649560, 2017). "Interestingly, cancer cells also express formyl-peptide receptors and the increased migration of these cells in response to formate or ALDH1L2 depletion reflects – at least in part – the production of formylated peptides and activation of formyl-peptide receptor signalling." (PMID 38698089, 2024). "In contrast, ALDH1B1, aldehyde dehydrogenase 1 family member L2 (ALDH1L2), and 18 family member A1 (ALDH18A1) are upregulated in most cancers." (PMID 40923024, 2025). "Taken together, these data demonstrate that K70Q mutant of ALDH1L2 suppresses CRC cell proliferation and sensitizes cancer cells to 5-Fu through disturbing cellular redox balance." (PMID 37507016, 2023). "It has been reported that ALDH1L2 catalyzed reaction is an important source of NADPH in mitochondria, which links this enzyme with cancer metastasis." (PMID 37507016, 2023). "Also, the regulatory mechanism of ALDH1L2 in cancer is also largely unknown." (PMID 37507016, 2023). "For example, ALDH1A2, ALDH2, ALDH3A2 and ALDH9A1 were downregulated in all tumors among the 5 cancer types, whereas ALDH1B1, ALDH1L2 and ALDH18A1 were most upregulated in tumor parts." (PMID 29426835, 2018).
cancer (continued). "Our data not only expand our understanding of the relationship between drug resistance and cancer metabolism, especially in the FOCM pathway, but also indicate that ALDH1L2 K70 could be a potential therapeutic site to prevent drug resistance." (PMID 37507016, 2023).
tumor (14 papers, 2018 to 2026). "Flow cytometry revealed that ALDH1L2 deficiency increased cell proportion in S phase while diminishing that in G0/G1 phase, indicating that ALDH1l2 deficient tumor cells were arrested at S phase." (PMID 39513106, 2024). "Subsequent results suggested that compared with the control group, ALDH1L2 knockdown markedly repressed the proliferation and migration capacity of tumor cells." (PMID 39513106, 2024). "ALDH1L2 knockdown significantly repressed the proliferation and migration capacity of tumor cells and increased the cell proportion in S phase." (PMID 39513106, 2024). "The objective of this current work was thus to determine the role played by the up-regulated ALDH1L2 in CSC obtained in vitro in the form of tumor sphere (TS)." (PMID 35565854, 2022). "We observed that both the percentage of positively stained cells and the intensity of Ki-67 staining were significantly high in ALDH1L2-knockdown tumours, even after irradiation (left, q)." (PMID 35597868, 2022). "We found that the volumes and weights of the tumours harvested from mice in the “ALDH1L2 silencing” group were significantly higher than those of mice in the control group, regardless of irradiation." (PMID 35597868, 2022). "Analysis of lysates from ADAM10 KO and WT U251 cells revealed changes consistent with those identified above, including downregulation of stem cell markers, such as DCLK1 and ALDH1L2, in keeping with the effects on Notch and Wnt pathway members, and the increased differentiation noted in tumours." (PMID 41226720, 2025). "Finally, ALDH1L2 was selected and its biological role in promoting tumor progression was validated in vitro." (PMID 39513106, 2024). "Our findings reveal an unknown 5-Fu-SIRT3-ALDH1L2 axis regulating redox homeostasis, and suggest that targeting ALDH1L2 is a promising therapeutic strategy to sensitize tumor cells to chemotherapeutic agents." (PMID 37507016, 2023). "In tumor spheres of the ALDH1L2 knockout cells, this bifurcation is expected to tilt towards the production of mitochondria formate, leading to reduced mitochondria NADPH production while simultaneously fueling the generation of cytosolic 10-formyl THF to supply the cytosolic methionine cycle." (PMID 35565854, 2022). "To further explore the role of K70 acetylation of ALDH1L2 on tumor growth and 5-Fu sensitivity in vivo, we injected reconstituted HCT116 cells with ALDH1L2 WT and ALDH1L2 K70Q into nude mice and analyzed their tumorigenesis and 5-Fu sensitivity." (PMID 37507016, 2023). "We revealed that SIRT3 increases ALDH1L2 activity, thus enhances CRC proliferation, which is consistent with previous reports on the tumor-promoting role of SIRT3 in CRC." (PMID 37507016, 2023). "The results showed that the mRNA expressions of ALDH1A3, ALDH1L2, ALDH2, and ALDH3A2 were obviously related to tumor purity." (PMID 34928471, 2022). "The oncogenic components, namely, ALDH1B1, ALDH1L2, CHSY1, CSGALNACT2, and GPX8, were progressively upregulated in more aggressive tumors, while the tumor suppressor hubs FBP1 and HPGD were downregulated as tumor aggressiveness increased." (PMID 40626022, 2025). "5-Fu-induced ALDH1L2 acetylation sufficiently inhibits its enzymatic activity and the production of NADPH and GSH, thereby leading to oxidative stress-induced apoptosis and suppressing tumor growth in mice." (PMID 37507016, 2023). "While in HCT116 cells, both ALDH1L1 and ALDH1L2 expression is minimal, suggesting that the folate pathway does not contribute substantially to NADPH, ALDH1L2 expression is found to be upregulated in several tumour types." (PMID 33707653, 2021).
ALDH1L2 also shares sentences with these, for which no sentence is quoted: bladder cancer (3 papers); adenocarcinoma (1); hepatocellular carcinoma (1); Insulin resistance (1); metabolic syndrome (1); metastatic melanoma (1); neuroendocrine carcinoma (1); nonalcoholic steatohepatitis (1); pancreatitis (1); prostate carcinoma (1); renal carcinoma (1); sarcopenia (1); small cell lung carcinoma (1); type 2 diabetes (1).